PROM1 (prominin 1)
Diseases named in the same sentence as PROM1 in open-access papers (continued):
Sharing a sentence is not in itself a finding about the gene and the disease.
Macular dystrophy (16 papers, 2014 to 2025). Macular dystrophy is a nonspecific term for retinal degeneration, generally confined to the macula, usually presumed of genetic origin. "Patients with the Prom1 R373C mutation (autosomal dominant Stargardt-like) exhibit macular dystrophy with three distinct phenotypes—central GA, multifocal GA, and bull’s eye maculopathy—suggesting an RPE cell-autonomous function of Prom1 in the human retina." (PMID 39513868, 2024). "In conclusion, the key clinical features associated with the PROM1 R373C variant can be summarized as varied type of macular dystrophy combined with variable degree of peripheral degeneration." (PMID 38072963, 2023). "In contrast to the RIMS1 variant, the PROM1 variant is highly enriched in patients with macular dystrophy and CORD9 and submitted 16 times to ClinVar (15 pathogenic and 1 likely pathogenic, accessed March 2021)." (PMID 35947379, 2022). "The loss-of-function Prom1 mutations result in inherited retinal dystrophies, including autosomal dominant and autosomal recessive retinitis pigmentosa, cone–rod dystrophies, and macular dystrophies." (PMID 39513868, 2024). "Retinitis pigmentosa (RP) and macular dystrophy (MD) are characterized by gradual photoreceptor death in the retina and are often associated with genetic mutations, including those in the prominin-1 (Prom1) gene." (PMID 34664634, 2021). "We searched the electronic patient records of our large inherited retinal disease cohort, quantifying numbers of males and females with the more common (non-ABCA4) inherited macular dystrophies (associated with BEST1, EFEMP1, PROM1, PRPH2, RP1L1, and TIMP3)." (PMID 38700873, 2024). "This is also true for the PROM1 gene, where recessive form resembles RP, while dominant PROM1 mutations leads to STGD4 and other forms of macular dystrophies." (PMID 36833218, 2023). "Heterozygous individuals in ABCA4 disease and control cohort harboring rare variants in macular dystrophy genes CDHR1, CHM, CRX, ELOVL4, PROM1, PRPH2, ROM1." (PMID 35353811, 2022). "Heterozygous individuals in ABCA4 disease and control cohort harboring variants with MAF<0.005 and CADD score >25, in each macular dystrophy gene CDHR1, CHM, CRX, ELOVL4, PROM1, PRPH2, and ROM1." (PMID 35353811, 2022). "Panel-based NGS was performed to identify potentially disease-causing genetic variants in previously identified retinal or macular dystrophy genes, including the five known STGD genes (ABCA4, PROM1, PRPH2, VMD2, and ELOVL4)." (PMID 33988224, 2021). "One family member, now known to have macular dystrophy, was previously reported not to harbor the RIMS1 p.Arg820His variant, but was unavailable for PROM1 testing (IV:9)." (PMID 35947379, 2022).
metastatic melanoma (16 papers, 2010 to 2024). A melanoma that has spread from its primary site to another anatomic site. "We previously reported that human FEMX-I metastatic melanoma cells released into the extracellular medium prominin-1-expressing microvesicles." (PMID 23767874, 2013).
astrocytoma (15 papers, 2010 to 2024). "The astrocytoma basis of GBM prompted the examination of prominin-1 expression in astrocytes in patient samples." (PMID 38258133, 2024).
Cirrhosis (15 papers, 2014 to 2025). A chronic disorder of the liver in which liver tissue becomes scarred and is partially replaced by regenerative nodules and fibrotic tissue resulting in loss of liver function. "Human cirrhotic and cirrhosis-associated HCC tissues showed an increase of IMP2 expression and of the progenitor cell markers SOX9, SPP1/osteopontin, CDH1/E-cadherin, AFP, PROM1/CD133, BEX1, EPCAM." (PMID 31555647, 2019).
pancreatic ductal adenocarcinoma (15 papers, 2008 to 2025). An infiltrating adenocarcinoma that arises from the epithelial cells of the pancreas. "Pancreatic ductal adenocarcinoma (PDAC) is another example of OXPHOS-dependent metabolism in CD133 (also known as PROM1)-expressing CSCs, when comparing with mature cancer cells." (PMID 29991569, 2018).
esophageal cancer (14 papers, 2010 to 2025). A primary or metastatic malignant neoplasm involving the esophagus. "Co-expression analysis showed that PROM1 was significantly co-expressed with ProSAPiP1, FAAH, and LTA in esophageal cancer." (PMID 31164716, 2020).
gastric adenocarcinoma (14 papers, 2010 to 2025). "Comparing the transcriptomes of isolated Prom1+ gastric stem cells and their Prom1− daughter cells from normal gastric mucosa and gastric adenocarcinomas, we observe that KCNQ1 is down-regulated and KCNQ2/3/5 genes are significantly up-regulated (Q < 0.05) in gastric adenocarcinomas in this model." (PMID 37748809, 2023). "PROM1+, but not PROM1−, cells isolated from P1KP gastric adenocarcinomas (P1KP-GAC) propagated these tumors as allografts, suggesting that PROM1+P1KP-GAC cells are the malignant counterparts of antral gland basal stem cells." (PMID 36175792, 2022).
gastric tumor (14 papers, 2010 to 2023). "In addition, the levels of CD133 (prominin 1) and ALDH1A1 (aldehyde dehydrogenase 1 family member A1) proteins, which are markers for gastric tumor stem cells, were notably increased in HGC-27-LR cells." (PMID 38012281, 2023).
retinitis pigmentosa (14 papers, 2011 to 2025). Retinitis pigmentosa (RP) is an inherited retinal dystrophy leading to progressive loss of the photoreceptors and retinal pigment epithelium and resulting in blindness usually after several decades. "A recently identified loss-of-function Prom1 variant (c.1354dupT) has shown a multi-phenotypic effect linked to cone–rod dystrophy and retinitis pigmentosa (RP)." (PMID 39513868, 2024). "PROM1-null variants are associated with autosomal recessive cone-rod dystrophy, retinitis pigmentosa and macular degeneration." (PMID 39355864, 2024). "Overall, the PROM1 variant is associated with multiple diseases with overlapping phenotypes, such as retinitis pigmentosa, cone–rod dystrophy, Stargardt-like macular dystrophy, and bull’s eye macular dystrophy." (PMID 38028590, 2023). "The resulting dendrogram captures some of the known phenotypic similarities in IRDs such as Stargardt phenocopy genes (ABCA4, PRHP2 and PROM1), retinitis pigmentosa genes (RPGR and USH2A) and achromatopsia genes (CNGA3 and CNGB3)." (PMID 40567353, 2025).
Stargardt disease (14 papers, 2014 to 2024). "Variants in ELOVL4 gen and PROM1 gen have also been described in Stargardt disease in an autosomal dominant pattern." (PMID 34051736, 2021). "In our previous study, we showed missing sequence coverage of some exons in the PROM1 gene from CNGS-based molecular diagnosis of putative Stargardt disease, one of the most common genetic forms of juvenile or early adult onset macular degeneration." (PMID 26794436, 2016). "In the case of Stargardt disease, a large proportion of mutations in ABCA4, ELOVL4 and PROM1 could be targeted with one or more of the currently described CRISPR-based approaches: genome editing, epigenetic repression, base editing or prime editing." (PMID 34439845, 2021).
ischemia (13 papers, 2012 to 2025). A hypoperfusion of the BLOOD through an organ or tissue caused by a PATHOLOGIC CONSTRICTION or obstruction of its BLOOD VESSELS, or an absence of BLOOD CIRCULATION. "PR1P is a small peptide derived from the extracellular domain of PROM1-derived peptide and improves cardiac function following ischemia." (PMID 37408649, 2023).
acute kidney injury (12 papers, 2009 to 2025). Sudden and sustained deterioration of the kidney function characterized by decreased glomerular filtration rate, increased serum creatinine or oliguria. "Urinary PROM1 secretion was confirmed by immunoblotting and was increased in patients with acute kidney injury (AKI) compared to healthy controls (p = 0.01)." (PMID 40894126, 2025).
renal carcinoma (12 papers, 2011 to 2023). A carcinoma arising from the epithelium of the renal parenchyma or the renal pelvis. "Moreover, we performed an overall survival analysis of patients with two different renal cancers (renal clear cell and renal papillary cell carcinoma) based on the renal Prominin 1 (CD133) gene expression normalized on the total CYP1B1 gene expression." (PMID 37371125, 2023). "Among these, CD133/prominin-1 is a cell-surface molecule thought to be a stem cell marker for multiple cancer types, including CNS, colon, hepatocellular, pancreatic, prostate, and renal cancer." (PMID 20981352, 2011).
retinal diseases (12 papers, 2011 to 2025). "Loss-of-function mutations in Prom1 cause a spectrum of retinal diseases, including autosomal dominant and recessive retinitis pigmentosa, cone-rod dystrophies, and macular dystrophies such as Stargardt disease type 4 (STGD4)." (PMID 41373691, 2025). "Future research on elucidating the molecular mechanisms of Prom1’s interactions with other cellular pathways will be essential for developing effective therapies for aAMD and other Prom1-associated retinal diseases." (PMID 39513868, 2024). "PROM1 mutations are associated with a range of inherited retinal diseases including autosomal recessive retinitis pigmentosa with or without macular degeneration and autosomal recessive or dominant cone rod dystrophy." (PMID 39353897, 2024). "This high phenotypic variability underscores the intricate nature of PROM1 p.R373C variant-associated retinal disease and suggests the probable influence of additional genetic, epigenetic, or environmental modifiers on the clinical phenotype." (PMID 38072963, 2023). "For example, biallelic loss-of-function variants in PROM1 can lead to a pan-retinal disease, whereas missense variants can cause a cone dystrophy." (PMID 36445968, 2022). "The vital role of Prominin-1 in the structural integrity of the photoreceptor OS is supported by the finding that mutations in Prominin-1 are connected to retinal diseases causing degeneration of the photoreceptors." (PMID 32213850, 2020). "It remains unclear whether Prom1-associated retinal diseases originate primarily in the RPE or the PRs with secondary RPE damage." (PMID 39513868, 2024). "Given the increasing number of retinal diseases associated with mutations in PROM1 gene, it is important to identify all the putative prominin-1 interacting partners (lipids or proteins), and cone-dominant zebrafish retina should be well suited to reveal those implicated in cone morphogenesis." (PMID 21407811, 2011). "Collectively, these cluster-specific changes reinforce a model where Prom1 loss drives inflammatory signaling, metabolic stress, and impaired autophagy, converging on pathways implicated in RPE dysfunction and retinal disease." (PMID 41373691, 2025). "Prom1-related retinal diseases, although relatively rare, significantly impact vision." (PMID 39513868, 2024). "Our findings highlight the importance of Prom1 as a central mediator in maintaining RPE health and offer promising directions for therapeutic advancements in retinal diseases." (PMID 39513868, 2024). "As of April 2025, there are no gene-targeted treatments for ELOVL4 or PROM1-related retinal diseases registered on clinicaltials.gov." (PMID 40960229, 2025).
skin cancer (12 papers, 2011 to 2025). "To investigate the relationship between prognosis and co-expression of PROM1 and PROM2, we retrieved clinical prognosis data from patients with various types of cancers, including breast, kidney, brain, ovarian, lung, and skin cancers, using OncoLnc, which accesses data from TCGA." (PMID 31164716, 2020). "Unlike PROM1, PROM2 mutations primarily occurred in skin cancer." (PMID 31164716, 2020).
acute lymphoblastic leukemia (10 papers, 2015 to 2024). Leukemia with an acute onset, characterized by the presence of lymphoblasts in the bone marrow and the peripheral blood. "Furthermore, PROM1 promoter activity is controlled by cis-regulatory elements such as enhancers in acute lymphoblastic leukemia (ALL)." (PMID 37922108, 2024).
liver fibrosis (10 papers, 2010 to 2024). "Because BDL-induced liver fibrosis was aggravated by global and liver-specific Prom1 deficiency but not by cholangiocyte-specific Prom1 deficiency, hepatocellular PROM1 was determined to be a negative regulator of liver fibrosis induced by TGFβ signaling." (PMID 36038590, 2022). "To address this discrepancy, we analyzed liver fibrosis in two different mouse models, global and liver-specific Prom1 deficiency." (PMID 36038590, 2022). "To understand the role of cholangiocytic Prom1 in liver fibrosis, we generated cholangiocyte-specific Prom1-deficient mice (Prom1f/f; Krt19-Cre) by crossing Prom1f/f mice (f/f) with transgenic Krt19-Cre mice." (PMID 36038590, 2022). "To determine the role of PROM1 in liver fibrosis, we generated liver-specific Prom1-deficient mice (Prom1f/f; Alb-Cre) by crossing Prom1f/f mice (f/f) containing two loxP sequences flanking exon 2 of Prom1 with Alb-Cre transgenic mice (Alb-Cre)." (PMID 36038590, 2022). "We also demonstrated that hepatocyte-specific overexpression of SMAD7 ameliorated BDL-induced liver fibrosis in liver-specific Prom1-deficient mice." (PMID 36038590, 2022). "We also demonstrate that PROM1 deficiency aggravated BDL-induced liver fibrosis and enhanced TGFβ signaling by reducing SMAD7 protein expression in hepatocytes." (PMID 36038590, 2022). "To understand the physiological function of PROM1 in the development of liver fibrosis, we induced liver fibrosis by BDL in global Prom1-deficient mice." (PMID 36038590, 2022). "The increased apoptotic bodies caused by PROM1 deficiency aggravate liver fibrosis via HSC activation." (PMID 36038590, 2022). "Because Prom1 deficiency was shown to protect against RRV-induced liver fibrosis in mice, the upregulation of Prom1 in HPCs might be necessary to promote biliary fibrosis." (PMID 36038590, 2022). "Because hepatocyte-specific SMAD7 overexpression ameliorated BDL-induced liver fibrosis in liver-specific Prom1 deficiency, hepatocellular TGFβ signaling might be required for the development of liver fibrosis." (PMID 36038590, 2022). "We next examined whether Prom1 deficiency in the liver influences liver fibrosis in BDL mice." (PMID 36038590, 2022). "Because 78% of TdTom-positive cells in the BDL livers expressed HNF4α, we concluded that hepatocytes are the major cell type in which Prom1 is upregulated during BDL-induced liver fibrosis." (PMID 36038590, 2022). "Based on all these data, we concluded that hepatocyte-specific PROM1 plays a central role in the regulation of TGFβ signaling and liver fibrosis via SMAD7 stabilization." (PMID 36038590, 2022). "We demonstrated that PROM1 plays a central role in TGFβ signaling and liver fibrosis by stabilizing SMAD7 using both global and liver-specific Prom1-deficient mice." (PMID 36038590, 2022). "We believe that our study will shed light on a novel physiological function of PROM1 in liver fibrosis." (PMID 36038590, 2022). "Our results suggest that hepatocyte-specific Prom1 is necessary to attenuate TGFβ-induced liver fibrosis by stabilizing SMAD7 and reducing TGFβ-induced apoptosis in hepatocytes." (PMID 36038590, 2022). "The serum assay showed that Prom1 deficiency aggravated BDL-induced liver fibrosis because the serum levels of AST, ALT, and bilirubin were further increased by Prom1 deficiency." (PMID 36038590, 2022). "Collectively, these data indicate that Prom1‐expressing HPCs functionally promote liver fibrosis during cholestatic liver injury." (PMID 32686913, 2020). "Thus, we conclude that PROM1 is necessary for the negative regulation of TGFβ signaling during liver fibrosis." (PMID 36038590, 2022). "Because PROM1 interfered with the molecular association of SMAD7 with SMURF2 and prevented SMURF2-induced SMAD7 ubiquitination and degradation, we conclude that PROM1 is necessary for the prevention of liver fibrosis by negatively regulating TGFβ signaling." (PMID 36038590, 2022).
liver fibrosis (continued). "In contrast, we showed that hepatocellular PROM1 protects against BDL-induced liver fibrosis." (PMID 36038590, 2022). "To determine whether the upregulation of PROM1 is an important regulator of liver fibrosis or simply the result of liver fibrosis, we analyzed BDL-induced liver fibrosis in global, liver-specific and cholangiocyte-specific Prom1-deficient mice." (PMID 36038590, 2022). "Thus, we focused on the role of PROM1 in hepatocytes, excluding its role in HSCs during liver fibrosis." (PMID 36038590, 2022). "However, in addition to TGFβ signaling, we cannot exclude the possibility that PROM1 controls many other modulators of hepatocyte death in the development of liver fibrosis." (PMID 36038590, 2022). "We also analyzed liver fibrosis after adenoviral overexpression of PROM1 or SMAD7." (PMID 36038590, 2022). "BDL-induced liver fibrosis was aggravated with increased phosphorylation of SMAD2/3 and decreased levels of SMAD7 by global or liver-specific Prom1 deficiency but not by cholangiocyte-specific Prom1 deficiency." (PMID 36038590, 2022).
macular degeneration (10 papers, 2010 to 2025). Loss of vision in the central portion of the retina (macula), secondary to retinal degeneration. "In our cohort, individuals carrying dominantly inherited PROM1 pathogenic variants typically exhibited a later development of macular degeneration and nyctalopia compared to those with recessive patterns." (PMID 41300751, 2025). "PROM1 plays a critical role in outer segment disc morphogenesis and PROM1 mutations cause a variety of photoreceptor diseases, such as RP, CORD, and macular degeneration." (PMID 33435268, 2021). "Interestingly, mutations in the human orthologues Prominin 1 (PROM1) and EYS are associated with autosomal-recessive retinitis pigmentosa and macular degeneration." (PMID 24705015, 2014).
renal cell carcinoma (10 papers, 2008 to 2024). "Fabp4, Gsn, Il6st, and Ly6e, were associated with nephritis and Col18a1, Prom1, and Scd1 with renal cell carcinoma." (PMID 25409434, 2014). "In renal cell carcinoma, expression of the stem cell protein CD133 also known as prominin-1 and the hyaluronan receptor CD44 are associated with CSCs." (PMID 33322354, 2020). "It was also determined that PROM1 and CD24 co-expression was limited in renal cell carcinoma (RCC) cell lines." (PMID 37108999, 2023).
meningioma (9 papers, 2012 to 2023). A generally slow growing tumor attached to the dura mater. "PROM1 is a pentaspan transmembrane glycoprotein that has been described by different research groups as a CSC factor in meningiomas." (PMID 31083655, 2019). "In our survey, PROM1 was markedly downregulated in DCC low expression meningiomas in five array expression studies." (PMID 31083655, 2019). "Whereas the average number of cells positive for both SOX2 and PROM1 significantly increased in GII + GIII meningioma cell lines, they significantly decreased in GII + GIII meningioma tissues compared to GI entities." (PMID 31083655, 2019). "An immunohistochemical study detected higher expression of nestin (NES), SOX2, and prominin 1 (PROM1), also known as CD133, in more progressive meningiomas." (PMID 31083655, 2019). "Previous work in meningiomas revealed different co-expression patterns of PROM1 and SOX2 in tissues compared to corresponding cell lines." (PMID 31083655, 2019). "In meningioma cultures, cells with pleomorphic characteristics show markedly increased numbers of CSCs scoring positive for PROM1 and SOX2, or AGR2 and BMI1." (PMID 31083655, 2019). "BMP/retinoic acid inducible neural specific 1 (BRINP1), and PROM1 were significantly downregulated in DCC low expression meningiomas in five studies." (PMID 31083655, 2019). "Similarly, meningioma cells expressing PROM1 revealed a higher proliferation rate and the formation of tumorspheres." (PMID 31083655, 2019). "In meningioma, the intracellular AGR2 expression was shown to co-localize with Bmi-1 and was regionally correlated with cancer stem cell markers Nestin, prominin 1 (CD133) and Sox2 in high-grade tumors." (PMID 31247903, 2019).